IKZF2 (IKAROS family zinc finger 2)
Diseases named in the same sentence as IKZF2 in open-access papers (continued):
Sharing a sentence is not in itself a finding about the gene and the disease.
nasal polyps (1 paper, 2024). "1; 95% CI = 1.9–112.17), IKZF2 rs12619285-AA (OR = 9.10; 95% CI = 1.7–75.78), FCER1B rs1441586-C (OR = 7.81; 95% CI = 1.16–73.45), and the presence of nasal polyps (OR = 9.16; 95% CI = 1.58–91.4)." (PMID 39125709, 2024).
parasitemia (1 paper, 2026). "TLR7 promotes protective humoral immunity during non‐lethal P. yoelii infection by enhancing Tfh differentiation, survival, and B‐cell help via the STAT3/Ikzf2 pathway, whereas TLR7 deficiency impairs antibody responses and increases parasitemia." (PMID 41461395, 2026).
T-cell acute lymphoblastic leukemia (1 paper, 2024). Acute lymphoblastic leukemia of T-cell origin. "A recent study highlighted the upregulation of IKZF2 in human cutaneous TCL and proposed its potential as a target gene for treatment, as well as in T-cell acute lymphoblastic leukemia in humans." (PMID 39911484, 2024).
type I diabetes (1 paper, 2024). "In this part, sequencing data from patients with type I diabetes were analyzed for IKZF2 expression in TR1, TFH, and Tconv cells." (PMID 38240853, 2024). "Moreover, the analysis of the PBMC database from type I diabetes patients revealed that TFH cells exhibited a definite expression of IKZF2 mRNA, although the expression level of IKZF2 in TFH cells was significantly lower than that in T regulatory type 1 (TR1) cells." (PMID 38240853, 2024).
vitiligo (1 paper, 2025). Generalized well circumscribed patches of leukoderma that are generally distributed over symmetric body locations and is due to autoimmune destruction of melanocytes. "Here, we identified 13 cell subsets and found that, compared with those in healthy individuals, Treg cells in progressive vitiligo patients are more abundant and express genes such as RTKN2, IKZF2, IL2RA, and STAM." (PMID 41438750, 2025).
tumor (15 papers, 2020 to 2026). "Targeting IKZF2 (the gene that encodes for the zinc finger protein HELIOS, a member of the Ikaros family of transcription factors), the novel glue degrader NVP-DKY709 (=DKY709) reduces tumor resident and circulating Treg cells." (PMID 38318526, 2024). "Moreover, ACP5, MAGEH1, TNFRSF9 and CCR8 were especially populated in tumor-infiltrating Tregs and IKZF2 was only highly expressed in paratumor-infiltrating Tregs." (PMID 35562760, 2022). "uncovered genes, including TLE4 and IKZF2, that are associated with T-cell exhaustion and effector function via screening of CAR-T cells, and identified genes, including RELA and NPLOC4, that are essential for tumor susceptibility to tumor killing via the reciprocal screening of GSCs." (PMID 35874698, 2022). "The transcriptional programs regulated by TBX21, ZNF595, FOSL2, ZNF83, ZNF484, IKZF2, and ELK3 were found to be significantly activated in tumor-reactive T cells." (PMID 39243082, 2024). "IKZF2 and IKZF5 were downregulated in the primary tumor, and IKZF1–3 expression decreased significantly as the T-stage or metastasis increased in SKCM." (PMID 36353107, 2022). "Specifically, Carma1, Rel, Nrp1, Ezh2, Senp3, and Ikzf2-null Treg all produce appreciable amounts of IFNγ and/or TNF in the tumor microenvironment." (PMID 33143070, 2020). "Cluster3 of both subsets (which we refer to as NK-innate-likeCD28− and CD28+, respectively), represented in peripheral blood and reduced at the tumor site, were characterized by the expression of NK-like markers KLRB1, KLRC3, and KIR2DL1, along with IKZF2 and ZBTB16 (PLZF)." (PMID 37898752, 2023). "In contrast, IKZF2 transactivation was enriched in CD30+ TMF, and IKZF2 has been reported to downregulate HLA type II genes in MF cells, which may help to CD30+ TMF cells escape the anti-tumor immunity." (PMID 37790936, 2023). "In contrast, mice with conditional ablation of Ikzf2, Pten, Rcor 1, or Rel, for instance, display no (or limited) signs of autoimmunity while enabling enhanced tumor clearance, perhaps indicating “safer” therapeutic targets in terms of adverse effects." (PMID 33143070, 2020). "Moreover, among different tumor locations, Ikaros genes were expressed at the highest levels in regional lymph nodes, IKZF1 and IKZF3 were expressed at the lowest levels in distant metastases, and IKZF2, IKZF4, and IKZF5 were expressed at the lowest levels in the primary tumor." (PMID 36353107, 2022).
cancer (7 papers, 2019 to 2025). A tumor composed of atypical neoplastic, often pleomorphic cells that invade other tissues. "The zinc finger transcription factor IKZF2 (Helios) is critical for the activity and stability of Tregs; its deficiency enhances immune responses to tumors in vivo, indicating IKZF2 may be an appealing target for cancer immunotherapy." (PMID 36499765, 2022). "We study the cooperative bindingmechanisms of molecular glue degraders, specifically cereblon (CRBN)modulators targeting Ikaros family zinc finger 2 (IKZF2), a transcriptionfactor implicated in cancer immunotherapy." (PMID 40326883, 2025). "We found that the significantly activated regulons were involved in T cell biology (RORC, TCF7, NFATC1, and LEF1) or disease pathogenesis (IKZF2 for CD30+ TMF and BATF3 for cALCL) or reported cancer biology (POUZAF1 and TSHZ2)." (PMID 37790936, 2023).
infection (3 papers, 2019 to 2026). The state of being infected such as from the introduction of a foreign agent such as serum, vaccine, antigenic substance or organism. "The CeD-dominated cluster C1 differentially expressed genes including TRGC2, IKZF2, GPR18, TRDC and KLHL42 that are associated with ‘infection’ related response pathways including ‘NOD-like receptor signaling pathway’ in gene ontology analysis." (PMID 35995787, 2022).
IKZF2 also shares sentences with these, for which no sentence is quoted: colorectal cancer (1 paper); combined immunodeficiency (1); Developmental delay (1); Evans syndrome (1); food allergy (1); gastric cancer (1); Hearing impairment (1); hemophagocytic lymphohistiocytosis (1); hypothyroidism (1); idiopathic thrombocytopenic purpura (1); IgA Nephropathy (1); inflammatory bowel disease (1); juvenile idiopathic arthritis (1); lupus nephritis (1); myeloma (1); Obesity (1); Osteopenia (1); ovarian tumors (1); Sepsis (1); Thrombocytopenia (1); urological diseases (1).